ENSG00000274006
Gene: Miscellaneous RNA gene on chromosome 11 (84,887,207 to 84,887,419, forward strand). Ensembl gene ENSG00000274006.
Gene Ontology:
Biological process: regulation of gene expression